CRP (C-reactive protein)
Diseases named in the same sentence as CRP in open-access papers (continued):
Sharing a sentence is not in itself a finding about the gene and the disease.
atherosclerosis (continued). "Secondly, we found that CRP immunoreactive proteins are present in the lesions of atherosclerosis of rabbits regardless of the lesion types." (PMID 24872599, 2014). "C-reactive protein (CRP) is a major biomarker of inflammation and a mediator of atherosclerosis." (PMID 24719806, 2014). "In fact, previous studies have reported that some components of the MD such as EVOO or nuts may down-regulate inflammatory markers related to atherosclerosis such as VCAM-1, ICAM-1, E- and P-Selectin, CRP and IL-6." (PMID 24925270, 2014). "The answers are becoming clearer and clearer: without doubt, plasma CRP levels are indeed increased and CRP is intimately present in the lesions of atherosclerosis." (PMID 24872599, 2014). "Thirdly, CRP immunoreactive proteins are present in all types of lesion of both rabbit and human atherosclerosis, but no CRP was detected in the lesions of mouse." (PMID 24872599, 2014). "The main objective of the study was to assess CIMT and hs-CRP levels as estimated markers of subclinical atherosclerosis and inflammation in prediabetic patients with no history of cardiovascular disease." (PMID 24353563, 2013). "Raised levels of CRP is a risk marker for atherosclerosis and CVD in many studies, though it is not clear if CRP is either protective or detrimental for disease development." (PMID 24194733, 2013). "In summary, the plasma 14,15-DHET levels in patients with CHD were significantly higher and were positive correlated with hs-CRP levels, suggesting that the decrease in 14,15-EET levels may be involved in the inflammatory reaction process in atherosclerosis." (PMID 24148690, 2013). "Beta2-GPI could combine with atherosclerosis factors, such as ox-LDL, CRP and Lp(alpha), to form corresponding stable complexes." (PMID 24238298, 2013). "C-reactive protein (CRP) and lysophosphatidylcholine (LPC) are phosphorylcholine-(PC)-containing oxidized phospholipids (oxPLs) found in oxidized LDL (oxLDL), which trigger pro-atherogenic activities of macrophages during the process of atherosclerosis." (PMID 23114023, 2012). "Smoking appears to contribute to the vascular inflammation characteristic of atherosclerosis, as reflected by higher serum C-reactive protein levels in smokers than in nonsmokers." (PMID 22347629, 2011). "In this model, voluntary exercise lowered IL6 and CRP in both diet groups but did not reduce the progression of atherosclerosis in the absence of dietary intervention." (PMID 21359188, 2011). "While its expression correlates with inflammatory markers, such as C-reactive protein, it does not predict atherosclerosis in humans." (PMID 21042583, 2010). "Unlike the Los Angeles Atherosclerosis Study, we did not detect an association between SNPs in LD blocks of ALOX5 on ultrasensitive CRP level (data not shown)." (PMID 20592751, 2010). "Results relating to atherosclerosis and CVD mortality in relation to CRP in RA are conflicting and CRP could have a role relating to thrombogenesis independent of atherogenesis." (PMID 20436910, 2010). "Patients with RA (n = 59) and healthy control subjects (n = 123), underwent measures of high sensitivity CRP, flow-mediated dilation (FMD, dependent on EDNO), intima-media thickness (IMT, a measure of subclinical atherosclerosis) and aortic pulse wave velocity (PWV, a measure of arteriosclerosis)." (PMID 20436910, 2010). "Moreover, the progression of atherosclerosis seems to be more severe in patients +CAD because they presented with a higher carotid IMT, which was also correlated with higher levels of CRP, IL-6, and sVCAM-1." (PMID 19584917, 2009). "The role of the Fcγ receptor IIa (FcγRIIa), a receptor for C-reactive protein (CRP), the classical acute phase protein, in atherosclerosis is not yet clear." (PMID 19480687, 2009).
atherosclerosis (continued). "Patients cancidate for Coronary Artery Bypass Grafting (CABG) have higher level of atherosclerosis, so we aimed to determine the Common Carotid Intima-Media Thickness (CCIMT), High Sensitivity C-Reactive Protein (hsCRP) level, and their relationship in CABG candidates." (PMID 18513415, 2008). "In several studies, it was found that CRP as a nonspecific marker for diagnosis of cardiovascular disease can indirectly influence on atherosclerosis." (PMID 18036243, 2007). "Infectious agents can contribute to the acceleration of atherosclerosis development by nonspecific mechanisms, such as hypercoagulation, increased production of adhesion molecules, and elevated C-reactive protein (CRP) levels." (PMID 17140429, 2006). "In addition, it did not showeffectiveness in reducing inflammation in patients with atherosclerosis—thelevels of IL-1β, IL-6 and CRP did not decrease." (PMID 40160593, 2025). "Chronically elevated CRP is not merely a marker but can contribute to the pathogenesis of systemic diseases such as atherosclerosis, cardiovascular disease, diabetes, and chronic kidney disease (CKD) by promoting endothelial dysfunction, oxidative stress, and immune dysregulation." (PMID 39859455, 2025). "Interestingly, the precise role of CRP in the development of endothelial dysfunction and atherosclerosis, which are considered inflammatory diseases, has not yet been fully elucidated." (PMID 38627621, 2024). "Lower concentrations of C-reactive protein may reduce the negative effects of smoking on atherosclerosis and related mortality." (PMID 38609915, 2024). "Consistent with other systemic inflammatory diseases such as atherosclerosis, our results showed that there were obviously a variety of biomarkers that increased in these patients, including WBC, neutrophil, monocyte, PLR, NLR, hs-CRP, and IL-6, and in addition, the level of lymphocyte decreased." (PMID 37525162, 2023). "In The Lupus Atherosclerosis Prevention Study (LAPS), 40 mg/day atorvastatin slowed not significantly atherosclerosis progression, but CRP decreased in the placebo group, more than in the atorvastatin group, which may be a crucial confounder." (PMID 36622519, 2023). "Moreover, our results corroborate findings from other studies showing that higher CRP levels do not have a causal relationship with the adjusted risk of CAD, HF, atherosclerosis, or MI." (PMID 37298077, 2023). "Thus, several inflammatory mediators such as high C-reactive protein (CRP) and circulating pro-inflammatory markers such as tumor necrosis factor-α (TNF-α) and interleukins are involved in the pathogenesis of IBD, as well as in atherosclerosis." (PMID 35892915, 2022). "Indeed, correlation networks analysis showed significant differences in the sphingolipidome of individuals with or without MetS based on their CRP levels, a key biomarker related with initiation, progression, and ischemic complications of atherosclerosis." (PMID 36578837, 2022). "By inputting hsa-miR-18a-5p, IL-10, CRP, VEGF-D, thrombomodulin, along with glucose to demonstrate a diabetic state into IPA software, miR-18a-5p was predicted to enhance the progression of atherosclerosis, infarction, and inflammatory response whilst inhibiting angiogenesis and blood coagulation." (PMID 36140236, 2022). "However, CRP is produced in the liver and not specific to atherosclerosis; rather, a high CRP level indicates the occurrence of an acute phase response, which can be induced by various inflammatory insults, such as infection, trauma, and allergy." (PMID 35406670, 2022). "ADMA rises through activation of inducible eNOS, and CRP is regulated by pro-inflammatory cytokines, though non-acute phase elevations may occur in several chronic inflammatory diseases, such as atherosclerosis and autoimmune diseases such as RA and SLE." (PMID 36293156, 2022).
atherosclerosis (continued). "However, the association between genetic variations in the CRP gene, estrogen use and CRP levels or early signs of atherosclerosis in young healthy individuals is not fully characterized." (PMID 35428187, 2022). "Furthermore, as was recently demonstrated on the rabbit model of atherosclerosis, oral supplementation of resveratrol has anti-inflammatory and anti-atherosclerotic effects, decreases serum levels of VEGF and CRP, and reduces atherosclerotic lesions’ formation and development." (PMID 35055117, 2022). "Therefore, the analysis of circulating EPCs might offer a new therapeutic target in PAD, while NPT synergistically with CRP and other conventional PAD biomarkers might provide useful information on the atherosclerosis initiation and progression." (PMID 34679610, 2021). "Furthermore, no significant influence on plasma concentrations of CRP was observed in participants with atherosclerosis after 400 μg/d of folic acid supplementation for 12 weeks." (PMID 34371837, 2021). "Lastly, our cohort of patients with non-NSA-ESUS had lower levels of CRP in comparison with strokes due to atherosclerosis; instead NSA-ESUS seem to have intermediate values, but not significantly different in comparison with both non-NSA ESUS and atherosclerotic strokes." (PMID 32849200, 2020). "C reactive protein (CRP), a circulating inflammatory marker, has a controversial role in the atherosclerotic disease, but it can transform oxidized LDLc into foam cells and can be a stable biomarker for low-grade inflammation, especially found in subclinical atherosclerosis." (PMID 32283588, 2020). "A possible reason for this is that the commonly used CHP, such as Gui-Zhi-Shao-Yao-Zhi-Mu-Tang, alleviate systemic inflammation by lowering the CRP, and erythrocyte sedimentation rate (ESR), which may decrease the progression of atherosclerosis, the main pathologic process of IS." (PMID 32194408, 2020). "Some inflammatory markers, such as CRP, ESR, and von Willebrand factor concentration, have been generally considered as having vital roles in the initiation, progression, and complication of atherosclerosis and as independent predictors of mortality and adverse cardiovascular events." (PMID 32375646, 2020). "Fifth, current markers that have recently been mentioned in the development of atherosclerosis, such as fibrinogen, sialic acid, serum protein amyloid a, and C-reactive protein, among others, could not be evaluated in our study." (PMID 31385674, 2019). "CRP antisense oligonucleotide treatment led to a significant reduction of CRP levels in rabbits; however, both aortic and coronary atherosclerotic lesions were not significantly changed, suggesting that inhibition of plasma CRP does not affect the development of atherosclerosis in rabbits." (PMID 31379851, 2019). "Also C-reactive protein (CRP), which is an acute phase reactant and a useful biomarker of CVD, might contribute to atherosclerosis development." (PMID 30558209, 2018). "Results of our study suggested that RBP4 was associated with risk factors of cardiovascular disorders such as HOMA-IR, TG, SBP, CRP, AI1, and AI2 and was a predictor for diabetic atherosclerosis, which implied that RBP4 could involve in many pathways on the formation of atherosclerosis." (PMID 30186876, 2018). "Finally, CRP is an established nonspecific prognostic inflammatory biomarker for patients with atherosclerosis." (PMID 30647800, 2018). "Higher CRP concentration over time, rather than spikes in CRP, may result in cardiovascular diseases (CVDs) and problems leading to atherosclerosis." (PMID 29951057, 2018). "CRP is commonly considered a sensitive biomarker of nonspecific systemic inflammation, but it may also have pleotropic effects in atherosclerosis through its effects on adhesion molecule expression, fibrinolysis, and endothelial dysfunction." (PMID 28771557, 2017).
atherosclerosis (continued). "However, none, including CRP, fibrinogen, IP-10 or MCP-1 remained associated with atherosclerosis in multivariable analyses." (PMID 28414714, 2017). "Hansson describes, for example, the development of an inflammatory cascade in atherosclerosis, involving, but not limited to, inflammatory cytokines (e.g. tumor necrosis factor alpha (TNF-α), interleukin-1 (Il-1)), interleukin-6 (Il-6), and acute-phase reactants (e.g. C-reactive protein (CRP))." (PMID 27270459, 2016). "The marginal role of CRP in mouse models of atherosclerosis did not help to improve knowledge." (PMID 27738391, 2016). "Other researchers described a significant negative correlation between ABI and CRP in patients aged below 60 with type 2 diabetes, and suggested that inflammation may play a role in the pathogenesis of atherosclerosis in these patients." (PMID 27834825, 2016). "Besides other known predictors such as CRP, LDL-cholesterol, and UA, WBC could be held responsible for the development of atherosclerosis." (PMID 26089882, 2015). "On the basis of quantitative analysis of atherosclerotic lesions, the data suggested that mouse CRP may even mediate atheroprotective effects rather than having a proatherogenic role in the two most widely used mouse models of atherosclerosis." (PMID 24872599, 2014). "Therefore, high levels of plasma and lesional CRP in Tg rabbits do not enhance the development of atherosclerosis." (PMID 24872599, 2014). "In conclusion, temporarily inhibiting the PCh-binding function of CRP along with facilitating localized presence of nonnative pentameric CRP could be a promising approach to treat atherosclerosis and myocardial infarction." (PMID 24948846, 2014). "In conclusion, we found that CRP lowering does not have significant influence on the initiation and progression of atherosclerosis in WHHL rabbits; thus, CRP may not be a therapeutic target for the treatment of atherosclerosis." (PMID 24872601, 2014). "Among numerous inflammatory markers, C-reactive protein (CRP), predominantly produced by hepatocytes under the stimulation of inflammatory cytokines such as interleukin 6 (IL-6), is one of the most well-validated markers and serves as an independent predictor in various stages of atherosclerosis." (PMID 23950953, 2013). "Parallel NOx and insulin increment and negative correlation of CRP and insulin in HC rabbits may be suggestive a protective role of hyperinsulinemia in early atherosclerosis." (PMID 23497719, 2012). "Atherosclerosis and NAFLD progression are both accompanied by inflammation development which involves several factors, including various chemokines (monocyte chemoattractant protein 1; MCP-1), cytokines (tumor necrosis factor-α; TNF-α), interleukin-6 (IL-6) and C-reactive protein (CRP)." (PMID 23226761, 2012). "Thus a lack of association between CRP and CVD would be expected in RA if CRP arising from a stimulus unrelated to atherosclerosis is unrelated to CVD." (PMID 20436910, 2010). "Our finding supports the concept that the hs-CRP level might not be related to atherosclerosis, but it may be a marker of plaque rupture and thrombosis." (PMID 19421644, 2009). "Given that chronic subclinicalinflammation is important in atherosclerosis and restenosis after PCI,inhibiting the proinflammatory adhesion molecule sICAM-1 and CRP levels by rosiglitazone,might have potentially beneficial effects in type 2 diabetic patients with CAD." (PMID 19107216, 2008). "Longer disease duration may contribute to chronic vascular remodelling, cumulative glucocorticoid or immunosuppressive exposure can suppress or modify FDG signal intensity, and varying levels of systemic inflammation (e.g., CRP elevation) may affect metabolic activity independent of atherosclerosis." (PMID 41375908, 2025). "However, we found that hs-CRP, but not fibrinogen, had a predictive role in atherosclerosis." (PMID 36983201, 2023).
atherosclerosis (continued). "Since we previously reported that CRP levels were more closely correlated with the degree of aortic atherosclerosis than that of coronary atherosclerosis, fortilin levels in patients with CAD may reflect not only coronary atherosclerosis, but also atherosclerosis in other vascular beds." (PMID 36012185, 2022). "Because of its retrospective design, inflammatory markers related to atherosclerosis (e.g., high-sensitivity C-reactive protein, interleukin-6, and adhesion molecules) were not studied, and a more detailed evaluation of the relationship between CSF and inflammation could not be performed." (PMID 34930134, 2021). "Finally, we did not assess other miRs which are also associated with vascular inflammation, such as miR-10a, miR-663, miR-92a, miR-21, and miR-1185, and we did not use high sensitivity C reactive protein, which is the most promising biomarker of preclinical atherosclerosis." (PMID 33917851, 2021). "Thus, our current findings using mutant CRP and previous findings using monomeric CRP, both molecules capable of binding to atherogenic LDL, indicate that structurally altered CRP protects against atherosclerosis; it is just that WT CRP does not exert a protective effect in most animal models." (PMID 32849641, 2020). "Hence, CRP and ESR may contribute to atherosclerosis progression through endothelial NO synthase inhibition, cytokine production, generation of reactive oxygen species by monocytes and neutrophils, vascular stiffness, T cell migration, and activation as suggested in other cardiovascular diseases." (PMID 33230950, 2020). "Additionally, in studies on cardiovascular diseases, such as coronary artery disease (CAD) and atherosclerosis, scholars found that adropin has a significant negative correlation with homocysteine (Hcy), hypersensitive C-reactive protein (hs-CRP), and levels of cytokines." (PMID 32190172, 2020). "CRP does not show an effect on the development of atherosclerosis likely because the inflammatory microenvironment in the arterial wall in animal models of atherosclerosis may not be appropriate in terms of pH and redox conditions and, therefore, the structure of CRP remains unchanged." (PMID 31379851, 2019). "Therefore, while the administration of exogenous human CRP to rodents has afforded essential insights regarding CRP biology, it does not allow for in vivo mechanistic studies of CRP in chronic inflammatory conditions such as IRI, transplant rejection, atherosclerosis, or AMD." (PMID 29946323, 2018). "Similarly, secondary prevention studies such as the Reversal of Atherosclerosis with Aggressive Lipid Lowering (REVERSAL) study show the use of higher statin doses (Atorvastatin 80 mg versus Pravastatin 40 mg) to significantly lower both LDL-C and CRP levels after 18 months of therapy." (PMID 24653858, 2014). "However, it is unknown whether L5 has effects similar to those of oxidized LDL, and a correlation between the roles of CRP and L5 in atherosclerosis has not been established." (PMID 23950953, 2013). "Furthermore, in this study baseline levels of CRP predicted the development of subclinical atherosclerosis which may not come as a surprise since CRP is a well known predictor of CVD and also of type 2 diabetes." (PMID 23536999, 2013). "However, the role of CRP as an aetiologic factor in atherosclerosis is not yet clear." (PMID 18564201, 2008). "The review found that TNF-α inhibitors significantly improved atherosclerosis markers such as CIMT, aPWV, FAI, and C-reactive protein (CRP), with reductions in these markers compared to no treatment, phototherapy, and IL-12/23 inhibitors." (PMID 39739136, 2024). "Although the patients had atherosclerosis, AN69 did not significantly alter the levels of CRP and LDL." (PMID 36769771, 2023). "C-reactive protein (CRP), for example, has been established to be central to human inflammation and atherosclerosis but not to mice." (PMID 34722670, 2021).